RPTN (repetin)
Description:
Involved in the cornified cell envelope formation. Multifunctional epidermal matrix protein. Reversibly binds calcium.
Synonyms: FLJ39117
Tractability: Antibody: its Gene Ontology location is reachable by antibodies, with high confidence; UniProt places it where antibodies can reach, with medium confidence.
Gene: Protein-coding gene on chromosome 1 (152,153,595 to 152,159,228, reverse strand). Ensembl gene ENSG00000215853.
Subcellular location: Secreted, extracellular space, extracellular matrix
Pathways (Reactome):
Developmental Biology: Formation of the cornified envelope
Gene Ontology:
Molecular function: calcium ion binding; transition metal ion binding
Cellular component: cornified envelope; cytosol
Genetic constraint (gnomAD): Loss-of-function variants: 5 observed, 4.96 expected, observed/expected ratio (o/e) 1.01, 90% interval 0.52 to 1.81. That is too few expected variants to judge how well the gene tolerates losing a copy. Missense variants: 860 observed, 949.52 expected, observed/expected ratio (o/e) 0.91, 90% interval 0.86 to 0.96. Synonymous variants: 293 observed, 327.55 expected, observed/expected ratio (o/e) 0.89, 90% interval 0.81 to 0.99.
Homologues: Orthologues: chimpanzee RPTN (90% identical), macaque RPTN (82% identical), rat Rptn (52% identical), mouse Rptn (49% identical). Paralogues in human: FLG2 (31% identical), HRNR (29% identical), FLG (28% identical).
Diseases named in the same sentence as RPTN in open-access papers:
RPTN is named in the same sentence as 9 diseases in open-access papers, as found by Europe PMC text mining. Sharing a sentence is not in itself a finding about the gene and the disease. The quoted sentences say what the papers report.
asthma (1 paper, 2024). "RPTN is upregulated in AD, and genetic variants in RPTN associate with AD severity, early onset of AD, itch, and concomitant asthma." (PMID 38344408, 2024).
food allergy (1 paper, 2017). Gastrointestinal disturbances, skin eruptions, or shock due to allergic reactions to allergens in food. "While our results confirmed the role of FLG null mutations in food allergy, a residual association was still detectable between FLG and the repetin gene (RPTN), which could point to additional genetic risk factors in this region." (PMID 29051540, 2017).
mastocytosis (1 paper, 2020). A clonal myeloproliferative neoplasm characterized by the proliferation and accumulation of neoplastic mast cells in one or multiple organs or organ systems. "Four SNPs were more prevalent (in ABCA2, OTX2-AS1, HLA-V, and PDE4DIP genes) and 5 were less prevalent (in RPTN, CYP2B6, OR51Q1, FTCD, and rs9828758 near RP11 genes) in mastocytosis patients compared to a control cohort." (PMID 32752121, 2020).
myocardial ischemia (1 paper, 2019). A disorder of cardiac function caused by insufficient blood flow to the muscle tissue of the heart. "The administration of rMK and rPTN has been proposed in a number of CNS and peripheral injuries, rending already significant effects in preclinical models, particularly in the case of myocardial ischemia and bone repair." (PMID 31031625, 2019).
papilloma (1 paper, 2023). A benign epithelial neoplasm that projects above the surrounding epithelial surface and consists of villous or arborescent outgrowths of fibrovascular stroma. "Noteworthy, the suprabasal-restricted proteins K1 and Repetin were identified as differentially expressed in papillomas from Tg46 animals compared to WT mice (p = 0.029 and p = 0.008, respectively), while the expression of basal-restricted K14 remained unaltered." (PMID 36693903, 2023).
RPTN also shares sentences with these, for which no sentence is quoted: cervical squamous cell carcinoma (1 paper); lung adenocarcinoma (1); psoriasis (1); stenosis (1).